HMGA1 (high mobility group AT-hook 1)
Diseases named in the same sentence as HMGA1 in open-access papers (continued):
Sharing a sentence is not in itself a finding about the gene and the disease.
cardiomyopathy (6 papers, 2018 to 2024). A disease of the heart muscle or myocardium proper. "The study aimed to investigate the role of HMGA1 in lipopolysaccharide-induced cardiomyopathy." (PMID 38430408, 2024). "However, the precise role of HMGA1 in sepsis induced cardiomyopathy (SIC) remains unintelligible." (PMID 32398950, 2020). "The important role of HMGA1 at these levels is supported by phenotypic studies in Hmga1-knockout mice, indicating that mice lacking HMGA1 develop cardiomyopathy, aberrant hematopoiesis, and defective pancreatic beta cell development." (PMID 30034366, 2018).
embryonal carcinoma (6 papers, 2010 to 2024). A non-seminomatous malignant germ cell tumor characterized by the presence of large germ cells with abundant cytoplasm resembling epithelial cells, geographic necrosis, high mitotic activity, and pseudoglandular and pseudopapillary structures formation. "The phenomenon of HMGA1/2 being over‐expressed has been documented in pluoripotent embryonal carcinoma, whereas there have been reports of a loss of HMGA1 expression in yolk sac tumor." (PMID 38507271, 2024). "HMGA1 is only detected in seminomas and embryonic carcinoma belonging to NSGCTs, and HMGA1 is overexpressed in most cases, which is helpful in differential diagnosis." (PMID 35864955, 2022).
endometrial carcinoma (6 papers, 2020 to 2025). A malignant tumor arising from the epithelium that lines the cavity of the uterine body. "Furthermore, the miR-197/HMGA1 axis was implicated in endometrial carcinoma progression accelerated by hsa_circ_0039569." (PMID 35130798, 2022). "In endometrial cancer, it binds to HMGA1 to promote c-MYC expression, accelerating the transcription of c-MYC-mediated glycolysis genes." (PMID 40379626, 2025). "The study confirmed that the protein and mRNA levels of HMGA1 are overexpressed in 46 cases of endometrial carcinoma (stages IA to IV), which is positively correlated with tumour stage, grade and size." (PMID 35864955, 2022). "Rescue experiments verified that the miR-197/HMGA1 axis was involved in the regulatory work of hsa_circ_0039569 in endometrial carcinoma." (PMID 35130798, 2022). "The results revealed that hsa_circ_0039569 and HMGA1 were elevated, while miR-197 was downregulated in endometrial carcinoma." (PMID 35130798, 2022). "We found that hsa_circ_0039569 promoted cell proliferation, migration and invasion in endometrial carcinoma, which occurred at least partially through sponging miR-197 to decrease the inhibitory effect of miR-197 on HMGA1." (PMID 35130798, 2022). "We focused our attention on the HMGA1 gene, a validated direct target of miR-214-3p in human cervical, colorectal, and endometrial cancer cell lines." (PMID 35406534, 2022). "This study demonstrated LINC00665 promoted endometrial carcinoma tumorigenesis and progression through interacting with HMGA1." (PMID 33407473, 2021). "In our future study, we would like to perform an overexpression of HMGA1 experiment and then observe its effect on endometrial carcinoma cell growth to strengthen our data." (PMID 33407473, 2021). "These motivated us to explore the interaction between LINC00665 and HMGA1 in endometrial cancer development." (PMID 33407473, 2021). "Taken together, these data indicated a close interaction between LINC00665 and HMGA1 in endometrial cancer." (PMID 33407473, 2021). "To conclude, we displayed circ_0067835 was increased in endometrial carcinoma and it sponged miR‐324‐5p to induce HMGA1." (PMID 33169939, 2020). "In our study, we displayed that circ_0067835 functions as a sponge absorbing miR‐324‐5p to modulate HMGA1 expression in endometrial carcinoma." (PMID 33169939, 2020). "A positive correlation between circ_0067835 and HMGA1 in endometrial cancer tissues was analysed using Spearmen's correlation." (PMID 33169939, 2020). "Increase in miR‐324‐5p remarkably depressed the proliferation, migration and invasion of endometrial cancer cells via inhibiting high mobility group A1 (HMGA1)." (PMID 33169939, 2020). "In conclusion, circ_0067835 can compete with miR‐324‐5p, resulting in HMGA1 up‐regulation, and therefore induce the development of endometrial cancer." (PMID 33169939, 2020). "Collectively, hsa_circ_0039569 may promote the development of endometrial carcinoma by serving as an endogenous sponge of miR-197, increasing HMGA1 expression and identifying a novel target for endometrial carcinoma treatment." (PMID 35130798, 2022). "In our study, we revealed that HMGA1 was notably elevated in endometrial carcinoma tissues." (PMID 35130798, 2022). "Moreover, hsa_circ_0039569 promoted endometrial carcinoma progression by sponging miR-197 and thus upregulating the expression of HMGA1." (PMID 35130798, 2022). "HMGA1 was confirmed as a potential prognostic factor in endometrial carcinoma." (PMID 35130798, 2022). "HMGA1 can promote tumor progression of endometrial carcinoma by activating Wnt/β-catenin signaling." (PMID 35130798, 2022). "shRNA of HMGA1 obviously restrained endometrial carcinoma cell growth and cell invasion." (PMID 33407473, 2021). "Furthermore, mechanistic analysis indicated LINC00665 regulates the expression of HMGA1, thereby inducing endometrial cancer progression." (PMID 33407473, 2021).
endometrial carcinoma (continued). "In addition, HMGA1 can facilitate endometrial cancer progression by regulating Wnt/β-catenin signaling." (PMID 33407473, 2021). "In addition, it was indicated that loss of circ_0067835 decreased proliferation, migration and invasion of endometrial carcinoma cells through sponging miR‐324‐5p to inhibit expression of HMGA1." (PMID 33169939, 2020). "Loss of circ_0067835 could significantly inhibit progression of endometrial carcinoma cells via targeting miR‐324‐5p/HMGA1 axis." (PMID 33169939, 2020). "The function of HMGA1 has been exhibited in multiple cancers, including endometrial carcinoma." (PMID 33169939, 2020). "Based on these data, we examined HMGA1 expression in endometrial carcinoma tissues and cells." (PMID 33169939, 2020). "HMGA1 is identified as a vital prognostic biomarker in endometrial cancer." (PMID 33169939, 2020). "Currently, we reported circ_0067835 was positively correlated with HMGA1 in endometrial cancer." (PMID 33169939, 2020). "In addition, in endometrial cancer, increase in HMGA1 can function as an effective prognostic factor." (PMID 33169939, 2020). "Overexpression of HMGA1 might be a potential prognostic factor in endometrial carcinoma." (PMID 35130798, 2022). "Taken together, these results demonstrated that hsa_circ_0039569 may play an oncogenic role in endometrial carcinoma progression by acting as a sponge of miR-197 and upregulating HMGA1 expression, which might support hsa_circ_0039569 as a potential therapeutic target for endometrial carcinoma." (PMID 35130798, 2022). "Thus, we suggested that LINC00665 may induce tumorigenesis by binding with HMGA1 in endometrial carcinoma." (PMID 33407473, 2021). "LINC00665 might promote endometrial carcinoma progression by positively modulating HMGA1." (PMID 33407473, 2021). "In addition, HMGA1 was predicted as a downstream target for miR‐324‐5p in endometrial carcinoma." (PMID 33169939, 2020). "It was confirmed that HMGA1 was decreased after knockdown of circ_0067835 in RL95‐2 cells, which was reversed by the increased HMGA1 in endometrial cancer cells." (PMID 33169939, 2020). "Subsequently, to explore the biological mechanism of LINC00665 in endometrial cancer, RIP assay was used to test whether HMGA1 protein interacted with LINC00665." (PMID 33407473, 2021).
leukemia (6 papers, 2012 to 2025). A malignant (clonal) hematologic disorder, involving hematopoietic stem cells and characterized by the presence of primitive or atypical myeloid or lymphoid cells in the bone marrow and the blood. "Increasing HMGA1 expression concurrent with progression in MPNs and refractory leukemia suggested a causal role for HMGA1 in MPN progression." (PMID 40076747, 2025). "Furthermore, HMGA1 deficiency in leukemia cell lines disrupts diverse leukemogenic properties, including proliferation, clonogenicity, and leukemic engraftment in immunosuppressed mice." (PMID 40076747, 2025). "Moreover, implantation of JAK2V617F AML cell lines with HMGA1 deficiency in immunosuppressed mice results in decreased engraftment of leukemic blasts in the bone marrow and spleen, together with a lower frequency of circulating leukemia blasts." (PMID 40076747, 2025). "In support of this, silencing HMGA1 via CRISPR/Cas9 or short hairpin RNA approaches demonstrates that HMGA1 is required for salient in vitro leukemia phenotypes, including proliferation and clonogenicity, in JAK2V617F AML cell lines." (PMID 40076747, 2025). "By contrast, restoring GATA2 in JAK2V617F AML cells with HMGA1 silencing partially rescues leukemia phenotypes, increasing clonogenicity and leukemic engraftment, without restoring proliferation rates in HMGA1-deficient cells." (PMID 40076747, 2025). "Given prior studies linking aberrant HMGA1 expression to refractory leukemia, its functional role in MPN leukemic transformation was not unexpected." (PMID 40076747, 2025). "In MPN leukemia models, HMGA1 is required for engraftment in the spleen and bone marrow and for clonal expansion." (PMID 40076747, 2025). "HMGA1 is also highly overexpressed in relapsed and refractory adult leukemia, including both lymphoblastic and myeloid leukemias." (PMID 40076747, 2025). "Three genes activated by v-Abl caught our attention due to their involvement in leukemia and cancer: Hmga1 (NM_016660), hnRNP A1 (NM_010447), and Hsp90ab1." (PMID 22693568, 2012).
lipoma (6 papers, 2016 to 2025). A benign, usually painless, well-circumscribed lipomatous tumor composed of adipose tissue. "HMGA2 and HMGA1 rearrangements have both been reported in multiple benign mesenchymal tumor types, including lipomas, endometrial polyps, and pulmonary chondroid hamartomas." (PMID 35822448, 2023). "For instance, 12q14–15 and 6p21 loci alterations have been shown to result in overexpression of HMGA2 and HMGA1 in pediatric lipomas." (PMID 36264345, 2022). "HMGA (HMGA1 and HMGA2) gene rearrangements, due to chromosomal translocations, have been described in human benign neoplasias of mesenchimal origin, including lipomas, whereas a truncated form of HMGA1 has been reported to induce proliferation in 3T3-L1 preadipocytes." (PMID 27445976, 2016). "A critical area of investigation is the identification of specific genetic alterations that contribute to the development of pediatric lipomas, such as those involving the loci 12q14–15 and 6p21, which are known to lead to the overexpression of genes like HMGA2 and HMGA1." (PMID 40729232, 2025).
lymph node metastasis (6 papers, 2014 to 2022). "Next, a comparative analysis of the cell cycle in the primary tumor and lymph node metastasis showed that the two CSC-like clusters (HMGA1-high and CD44/MYC-high) had an increased cell division index in lymph node metastasis." (PMID 35611554, 2022). "Meanwhile, HMGA1 expression was increased in molecular phenotypes with poor prognosis (ER-, PR-, and HER2+) and associated with high-grade group, lymph node metastasis, and NPI (Nottingham Prognostic Index)." (PMID 36479041, 2022). "Moreover, high HMGA1 expression was significantly correlated with lymph node metastasis and CA199 in CCAs." (PMID 34716319, 2021). "Additionally, high HMGA1 was significantly related with lymph node metastasis and Nottingham Prognostic Index (NPI)." (PMID 36479041, 2022).
neuroblastoma (6 papers, 2000 to 2022). Neuroblastoma (NB) is the most common solid, extracranial childhood tumor. "The important transcriptional target of MYCN in neuroblastoma is the high mobility group A1 (HMGA1) oncogene." (PMID 33194665, 2020). "Fort this reason, a detailed investigation of the HMGA1 expression in neuroblastoma cell lines treated with ATRA and LOX/COX inhibitors is needed." (PMID 20459794, 2010). "According to published data, retinoic acid may increase HMGA1 expression in RA-resistant neuroblastoma cells, but it inhibits this expression in cells undergoing RA-induced neuronal differentiation." (PMID 20459794, 2010). "Nevertheless, HMGA1 expression is influenced by MYCN status in neuroblastoma cells: this gene is significantly more expressed in MYCN-amplified neuroblastomas and it might be also activated by c-MYC or other transcription factors." (PMID 20459794, 2010). "In neuroblastoma, HMGA1 is regulated by MYCN in the MYC protein family, and abnormal expression of MYCN affects overexpression of HMGA1." (PMID 35629376, 2022). "Subsequent studies demonstrated that HMGA1 interacts with the RB protein and interferes with RB-mediated repression of E2F1 transcription and cell cycle progression in neuroblastoma cells." (PMID 22053823, 2011). "Since the major function of MYCN is as a transcription factor, further studies are needed to clarify whether HMGA1, a target of MYCN, is involved in the cell division fate of human neuroblastoma cells." (PMID 33194665, 2020).
leiomyoma (5 papers, 2015 to 2024). A well-circumscribed benign smooth muscle neoplasm characterized by the presence of spindle cells with cigar-shaped nuclei, interlacing fascicles, and a whorled pattern. "In line with the 3′RNA‐sequencing results, the structural variant analysis detected an HMGA2 rearrangement in eight leiomyomas, an HMGA1 rearrangement in four leiomyomas, and a PLAG1 rearrangement in four leiomyomas." (PMID 35822448, 2023). "As we detected biallelic loss of FH in two leiomyomas previously reported to overexpress HMGA1, we explored the expression pattern of HMGA1 in our dataset as well." (PMID 33352722, 2020). "Mutations of MED12 were found in leiomyomas with a normal karyotype, with deletions or rearrangements of the long arm of chromosome 7 as sole anomaly, and with 6p21∼23 abnormalities leading to HMGA1 rearrangement/overexpression, and it was concluded that they precede the chromosomal aberrations." (PMID 28591699, 2017). "One of these clusters consisted of 16 leiomyomas that showed high expression of HMGA1 and the other consisted of 12 leiomyomas that displayed exceptionally high expression of PLAG1, but low expression of both HMGA1 and HMGA2." (PMID 35822448, 2023). "Again, the samples clustered clearly into four similar groups, and the two HMGA1 overexpressing leiomyomas displayed clear expression patterns of leiomyomas of the FH subtype." (PMID 33352722, 2020). "Two samples, originally classified as HMGA1 overexpressing leiomyomas, displayed clear expression patterns of leiomyomas of the FH subtype." (PMID 33352722, 2020). "Chromosome rearrangements of 8q11∼13 but without concomitant involvement of 12q13∼15 (where HMGA2 maps) or 6p21 (where the HMGA1 gene is situated) was reported in six uterine leiomyomas, one leiomyoma of the vagina, and one intraabdominal leiomyoma." (PMID 28591699, 2017). "In addition to rearrangements of HMGA1, HMGA2, and PLAG1, we identified biallelic loss of DEPDC5 in one leiomyoma with an HMGA2 rearrangement and in another leiomyoma with an HMGA1 rearrangement." (PMID 35822448, 2023). "It is tempting to speculate that leiomyomas of the FH subtype may in part promote tumorigenesis through dysregulation of HMGA1." (PMID 33352722, 2020). "However, high expression of AKR1B10 was observed in two fresh frozen samples that were originally classified as HMGA1 overexpressing leiomyomas." (PMID 33352722, 2020). "In a few leiomyomas, we detected HMGA2 or HMGA1 to be combined with a candidate partner gene in opposite directions." (PMID 35822448, 2023). "To conclude, we have here confirmed that leiomyomas with an HMGA2, HMGA1, or PLAG1 rearrangement share multiple molecular features, including similar gene expression patterns and shared translocation partners." (PMID 35822448, 2023). "We identified chromosomal rearrangements targeting either HMGA2, HMGA1, or PLAG1 in all 16 tumors, demonstrating that it is possible to detect chromosomal driver alterations in archival leiomyoma specimens as old as 18 years." (PMID 35822448, 2023). "3′RNA‐sequencing of 111 leiomyomas that were previously classified as triple‐negative revealed high HMGA1 or HMGA2 expression in a subset of leiomyomas." (PMID 35822448, 2023). "A few leiomyomas displayed breakpoints downstream of HMGA2 and HMGA1, suggesting that also downstream rearrangements could result in their upregulation." (PMID 35822448, 2023). "In a recent study, MED12 mutations were also found in 34% of leiomyoma/leiomyomatosis in pelvic/retroperitoneal sites but there was no information about the status of HMGA2 and HMGA1." (PMID 25621995, 2015). "Moreover, overexpression of HMGA1 and/or HMGA2 is in leiomyomas common finding." (PMID 37466765, 2024). "RAD51B may be a fusion partner of HMGA2 and HMGA1 but can occur in fusion with other genes including NUDT3 and seems to be a potential driver event in these tumors mutually exclusive with other driver aberrations defining molecular leiomyoma subtypes." (PMID 37466765, 2024).
leiomyoma (continued). "Unlike HMGA2 rearrangements, HMGA1 and PLAG1 rearrangements are rare in leiomyomas and may co‐occur with MED12 mutations, suggesting that they are secondary events related to tumor progression." (PMID 35822448, 2023). "Although some studies have indicated that HMGA1 overexpressing leiomyomas result in a distinct expression profile, our observations are compatible with a recent RNA‐sequencing study on 276 leiomyomas in which most HMGA2 and HMGA1 overexpressing leiomyomas clustered together." (PMID 35822448, 2023). "However, none of the samples with an HMGA1 or PLAG1 rearrangement in this study harbored an alteration in a well‐established leiomyoma driver gene and all displayed expression features associated with leiomyomas of the HMGA2‐subtype." (PMID 35822448, 2023). "This motivated us to explore the expression pattern of HMGA1 in our FFPE dataset, revealing significant upregulation of HMGA1 in leiomyomas of the FH subtype, but not in leiomyomas of the MED12 and HMGA2 subtypes." (PMID 33352722, 2020).
lymphoma (5 papers, 2012 to 2022). A malignant (clonal) proliferation of B- lymphocytes or T- lymphocytes which involves the lymph nodes, bone marrow and/or extranodal sites. "Its role in transformation has been documented extensively elsewhere: HMGA1 is elevated in poorly differentiated carcinomas where its expression is related to a poor prognosis; HMGA1 induces oncogenic transformation in cultured cells and causes lymphomas in transgenic mice." (PMID 22745689, 2012). "Mechanistic studies have demonstrated that circ-NSUN2 can promote lymphoma progression by affecting Wnt pathways through the regulation of HMGA1." (PMID 35116058, 2021). "Mechanistic results suggest that circ-NSUN2, regulated by the transcription factor NRF1, can promote lymphoma progression by stabilizing the HMGA1-activated Wnt pathway." (PMID 35116058, 2021). "Studies are in progress to evaluate the expression levels of HMGA1 pseudogenes in human lymphomas." (PMID 32341372, 2020). "Surprisingly, HMGA1 did not result upregulated by HMGA1P7 overexpression in the analysed pathological spleens, suggesting that pseudogene-induced lymphomas were based on other molecular targets already described." (PMID 32341372, 2020).